PRICKLE1 (prickle planar cell polarity protein 1)
Diseases named in the same sentence as PRICKLE1 in open-access papers (continued):
Sharing a sentence is not in itself a finding about the gene and the disease.
leiomyoma (1 paper, 2024). A well-circumscribed benign smooth muscle neoplasm characterized by the presence of spindle cells with cigar-shaped nuclei, interlacing fascicles, and a whorled pattern. "In an effort to identify the mechanism of loss of REST in leiomyoma, we focused on PRICKLE1, a WNT/PCP protein that associates with REST." (PMID 39314474, 2024). "Crucially, mice exposed neonatally to environmental estrogens, proven risk factors for fibroids, expressed lower levels of PRICKLE1 and REST in the myometrium." (PMID 39314474, 2024). "How the missense mutations to MED12 reported in leiomyoma affect PRICKLE1 and the WNT/PCP pathway, in addition to REST localization and function are currently unknown." (PMID 39314474, 2024). "The combined loss of both PRICKLE1 and REST in leiomyomas and the mislocalization of REST in leiomyoma cells point to a direct role for PRICKLE1 in the loss of REST in uterine fibroids." (PMID 39314474, 2024). "Taken together, we identify a novel pathway that connects environmental estrogen exposure, suppression of PRICKLE1, loss of REST-dependent epigenetic control, and aberrant gene expression in leiomyomas." (PMID 39314474, 2024). "Conversely, overexpression of PRICKLE1 resulted in the restoration of REST in cultured primary leiomyoma smooth muscle cells (LSMCs)." (PMID 39314474, 2024). "PRICKLE1 expression is markedly lower in leiomyomas, and the suppression of PRICKLE1 significantly down regulates REST protein levels." (PMID 39314474, 2024). "Gene expression analysis in replicates of matched myometrial and leiomyoma samples from patients confirmed the reduced expression of PRICKLE1 in ULs compared to that in myometrial tissue." (PMID 39314474, 2024). "Collectively, our results identify a novel link between estrogen exposure and PRICKLE1/REST-regulated tumorigenic pathways in leiomyomas." (PMID 39314474, 2024). "PRICKLE1 protein levels were also significantly reduced in leiomyoma as indicated by immunoblot and immunofluorescence analyses." (PMID 39314474, 2024). "Interestingly, the distal site was associated with increased H3K27Me3 and EZH2 in leiomyoma samples, showing a putative role for EZH2 in the epigenetic regulation of PRICKLE1 in UL." (PMID 39314474, 2024). "Interestingly, reduced levels of PRICKLE1 also mirror the low REST levels in leiomyoma compared to myometrial tissue." (PMID 39314474, 2024). "Additionally, we identify a direct role for the polycomb repressive complex protein EZH2 (enhancer of zeste homolog 2) in the repression of PRICKLE1 in leiomyoma smooth muscle cells." (PMID 39314474, 2024). "In contrast to this hypothesis, our results indicated that EZH2 expression is significantly upregulated in leiomyoma samples both at mRNA and protein levels and this upregulation was inversely correlated with the expression of PRICKLE1 and REST." (PMID 39314474, 2024). "Furthermore, siRNA knockdown of EZH2 in cultured primary LSMCs resulted in the increase of PRICKLE1 expression, showing that EZH2 is overexpressed in leiomyomas, and may play a role in the repression of PRICKLE1." (PMID 39314474, 2024). "Conversely, overexpression of Flag-tagged PRICKLE1 in cultured primary LSMCs led to a matching restoration of REST expression without altering REST mRNA expression, confirming that the loss of PRICKLE1 expression in leiomyoma is linked to the destabilization of REST." (PMID 39314474, 2024). "Our results support a novel ERα/ EZH2 – PRICKLE1 mediated, REST- target-specific gene derepression model in the pathogenesis of leiomyomas." (PMID 39314474, 2024). "Relevant to the role of PRICKLE1 in regulating the stability of REST without affecting its mRNA expression, we had shown earlier that the loss of REST protein expression in leiomyomas does not accompany a corresponding decline in its mRNA expression." (PMID 39314474, 2024).
leiomyoma (continued). "We observed that upon siRNA-mediated knockdown of PRICKLE1 in cultured primary MSMCs, REST expression was correspondingly reduced, indicating that the low PRICKLE1 levels in leiomyomas may indeed trigger the decline in REST stability and function." (PMID 39314474, 2024).
leukemia (1 paper, 2021). A malignant (clonal) hematologic disorder, involving hematopoietic stem cells and characterized by the presence of primitive or atypical myeloid or lymphoid cells in the bone marrow and the blood. "Next, we explored the expression of PRICKLE1 in leukemia cell lines using qRT-PCR and western blotting." (PMID 34001134, 2021).
lung carcinoma (1 paper, 2016). "Similar to what we show for Prickle1, it has been reported that Scribble, another PCP protein, may inhibit β-catenin signaling and act as a tumor suppressor in mammary gland, prostate and lung cancer." (PMID 27036398, 2016).
metastatic carcinoma (1 paper, 2021). A carcinoma which has spread from the original site of growth to another anatomic site. "Of note, PRICKLE1 interacted with PARD6A, a cell membrane protein which plays a role in cell polarization and the epithelial-to-mesenchymal transition (EMT) that represents the invasive phenotype in metastatic carcinomas." (PMID 34001134, 2021).
nasal polyp (1 paper, 2023). "No immunoreactivity was observed in either the turbinate mucosa or nasal polyp for Prickle1 or Vangl1." (PMID 38232516, 2023).
orofacial clefting (1 paper, 2021). "PRICKLE1, when disrupted, has been linked to craniofacial malformations, such as orofacial clefting (OFC), in animal models and in humans." (PMID 34434215, 2021).
triple-negative breast carcinoma (1 paper, 2021). An invasive breast carcinoma which is negative for expression of estrogen receptor (ER), progesterone receptor (PR), and human epidermal growth factor receptor 2 (HER2). "In accordance with our findings, previous studies have revealed that the mRNA level of PRICKLE1 was substantially elevated in solid tumors, such as basal breast cancers, and triple-negative breast cancers." (PMID 34001134, 2021).
uterine fibroids (1 paper, 2024). "To elucidate the role of PRICKLE1 in REST stability and to establish a molecular mechanism for their concomitant loss in uterine leiomyomas, we tested whether modulating PRICKLE1 expression levels had an effect on REST protein levels." (PMID 39314474, 2024). "We found that uterine leiomyomas expressed significantly lower levels of PRICKLE1, and its expression mirrored that of REST." (PMID 39314474, 2024). "Conversely, PRICKLE1 and HB-EGF, two of the REST pathway associated genes with putative roles in the regulation of REST, were down regulated in uterine leiomyomas." (PMID 39314474, 2024). "PRICKLE1 regulates REST expression in uterine leiomyomas at protein level." (PMID 39314474, 2024). "The widespread destabilization and loss of REST in the absence of PRICKLE1 expression seen here in uterine leiomyomas is entirely novel, and may provide future therapeutic approaches for restoring REST function." (PMID 39314474, 2024).
Vestibular schwannoma (1 paper, 2021). A vestibular schwannoma (also known as acoustic neuroma, acoustic neurinoma, or acoustic neurilemoma) is a benign, usually slow-growing tumor that develops from the VIIIth cranial nerve supplying the inner ear. "PRICKLE1 mRNA is significantly down-regulated in vestibular schwannomas, while GALR1 is abundant in neuroactive ligand-receptor interactions, and both PRICKLE1 and GALR1 are targets of hsa-miR-30c-5p and hsa-miR-30a-5p, suggesting that hsa-miR-30 may play a key role in vestibular schwannomas." (PMID 33673851, 2021).
cancer (12 papers, 2016 to 2024). A tumor composed of atypical neoplastic, often pleomorphic cells that invade other tissues. "PRICKLE1 was shown to participate in the regulation of the mammalian target of the rapamycin (mTOR) signalling pathway in cancer." (PMID 37358815, 2024). "Downregulating PRICKLE1 expression in cancer cells significantly reduced migration speed; however, upregulating Prickle1 expression does not always increase cell migration." (PMID 37358815, 2024). "This study demonstrates the importance of the evolutionarily conserved interaction between Prickle1 and Ect2, which appears to be reactivated during tumorigenesis to promote cancer cell dissemination and metastasis." (PMID 30971775, 2019). "Altogether, this depicts PRICKLE1 as a master regulator of localised expression and regulation of signalling events in migratory cancer cells." (PMID 30971775, 2019). "On the other hand, PRICKLE1 can attenuate Wnt/β-catenin signaling through the degradation inactivation of β-catenin and may act as a tumor suppressor in some cancers." (PMID 36861110, 2022). "PRICKLE1 promotes cancer cell transmission through interaction with mTORC2." (PMID 34926458, 2021). "Previous studies demonstrated that PRICKLE1 regulates two pathways in cancer." (PMID 26939613, 2016). "It is not clear which mTOR signalling branch is involved in PRICKLE1-dependent cancer cell motility." (PMID 37358815, 2024).
tumor (8 papers, 2013 to 2024). "However, PRICKLE1 has also been found to have anti-tumour properties in liver cancer and neuroblastoma, where its overexpression has been associated with decreased tumour size." (PMID 37358815, 2024). "PRICKLE1 has been reported to be a negative regulator of the Wnt/beta-catenin signaling pathway and is a putative tumor suppressor gene in HCC." (PMID 34660596, 2021). "We hypothesized that the loss of PRICKLE1 expression in LSMCs is mechanistically linked to the loss of REST and smooth muscle tumor development in the uterus." (PMID 39314474, 2024). "In different tumor cells, PRICKLE1 has different regulatory roles." (PMID 36861110, 2022). "Given the critical role that PRICKLE1 plays in the stability of REST, the long-term repression of this tumor suppressor pathway by environmental estrogens could trigger genetic and epigenetic instability that promotes uterine fibroid pathogenesis." (PMID 39314474, 2024).
PRICKLE1 also shares sentences with these, for which no sentence is quoted: acute myeloid leukemia (1 paper); adenoma (1); Alzheimer disease (1); Arthritis (1); Ataxia (1); colon cancers (1); depression (1); encephalitis (1); esophageal cancer (1); esophageal squamous cell carcinoma (1); focal epilepsy (1); infection (1); Intellectual disability (1); liposarcoma (1); liver cancer (1); lung adenocarcinoma (1); malignant peripheral nerve sheath tumor (1); myoclonic epilepsies (1); osteoarthritis (1); Progressive myoclonic epilepsy (1); rectal cancer (1); round cell liposarcoma (1); schizophrenia (1); Tourette syndrome (1); Uterine leiomyoma (1).